FOXO1 (forkhead box O1)
Diseases named in the same sentence as FOXO1 in open-access papers (continued):
Sharing a sentence is not in itself a finding about the gene and the disease.
cardiac diseases (4 papers, 2018 to 2026). "We further intended to design a potential drug against FOXO1, a strong transcription factor which interacts with other key genes associated with lethal heart disorders in PS." (PMID 30423812, 2018). "One thing is evident clearly though multiple studies—there is a direct and indirect involvement of FOXO1 in heart disease." (PMID 30423812, 2018). "FoxOs, such as Foxo1, 3, and 4, play important roles in cardiac diseases." (PMID 32768667, 2020). "Molecular network analysis and protein–protein interaction study indicated FOXO1 as strong transcription factor which interacts with other key genes like GATA4, CITED and TBX5 located on different chromosomes but associated with lethal heart disorders in PS." (PMID 30423812, 2018).
colon (4 papers, 2021 to 2022). "Studies have shown that low levels of FOXO1 are closely related to digestive system neoplasms." (PMID 34277395, 2021).
colorectal (4 papers, 2020 to 2025). "In a previous study, miR-96 has been substantiated to contribute to colorectal carcinogenesis via targeting TP53INP1, FOXO1 and FOXO3a." (PMID 33183350, 2020).
hematological malignancies (4 papers, 2019 to 2025). "Here, we review the role of FoxO1 in normal and malignant B cells, and the results from preclinical studies of FoxO1 inhibition in hematological malignancies." (PMID 39533662, 2025). "FoxO1 activity can be inhibited by small molecules that exhibited promising preclinical activity in hematological malignancies." (PMID 39533662, 2025). "Overall, it has been proposed that FoxO1 inhibition might be a potential therapeutic approach in several hematological malignancies." (PMID 39533662, 2025). "Importantly, up-regulation of the miR-150 expression in hematological malignancies is considered a promising therapeutic approach, warranting further investigations of antitumor effects of FOXO1 inhibitors." (PMID 31557894, 2019). "Apart from the regulation of cell-cycle arrest, FOXO1 is also a potent transcriptional activator of RAG1, which is critical for tumorigenesis and survival in hematological malignancies." (PMID 36675119, 2023).
myopathy (4 papers, 2017 to 2024). A disease of the muscle in which the muscle fibers do not function properly. "An understanding in molecular mechanisms of FoxO1 in muscle may develop new therapeutic approaches that can be used to prevent myopathies, such as muscle atrophy, in spite of great challenges that remain to be conquered." (PMID 27793012, 2017). "Whilst FOXO1 inhibition enhanced the myogenic program in both ALS and VCP-myopathy myoblasts, particularly in VCP-myopathy with a 2.75-fold increase in the differentiation index, we did not observe mislocalization of FOXO1 to the nucleus or a negative impact on myogenesis." (PMID 39283487, 2024).
adenocarcinoma (3 papers, 2022 to 2023). A common cancer characterized by the presence of malignant glandular cells. "An in vivo study demonstrated that, in adenocarcinoma, melatonin exerted abilities of regulating the interplay between forkhead box protein O1 (FoxO1), miR96, and miR215 signaling." (PMID 35409137, 2022).
head and neck neoplasm (3 papers, 2013 to 2024). A benign or malignant neoplasm that affects the anatomic structures of the head and neck region. "PAX3::FOXO1 inhibits the Hippo/MST1 signaling pathway, and genetic removal of Mst1/Mst2 Hippo pathway members in the Myf6-Cre Pax3::Foxo1 mouse model increased the frequency of head and neck tumors." (PMID 38916046, 2024).
vascular disorder (3 papers, 2017 to 2023). A general term used to describe any disease affecting blood vessels]. "The loss of Foxo1 transcriptional activity has been implicated in multiple vascular disorders." (PMID 36145233, 2022).
blood cancer (2 papers, 2022 to 2023). "To test whether enforced FOXO1 expression is sufficient to induce EBF1, IRF4, or PAX5 expression in non-B-lineage blood cancer cells, we next transduced lentivirus encoding FOXO1 into the AML cell lines HEL and THP1, which express negligible levels of EBF1, FOXO1, IRF4, and PAX5." (PMID 36282572, 2022).
retinopathy (2 papers, 2019 to 2025). "To see whether endothelial MST1 and FOXO1 has a significant role in pathologic angiogenesis, we employed an oxygen-induced retinopathy (OIR) model." (PMID 30783090, 2019).
benign tumors (1 paper, 2019). "To evaluate the protein expressions of FOXO1 and PAX3 in EOC, we analyzed FOXO1 and PAX3 protein levels in 212 EOC tissues, 57 borderline tumors, 153 benign tumors, and 79 nonadjacent normal epithelial tissues by IHC." (PMID 31823759, 2019). "Our IHC analysis showed that FOXO1 is significantly upregulated in EOC tissues compared to borderline tumors, benign tumors, and nonadjacent normal epithelium (all p < 0.001)." (PMID 31823759, 2019). "Finally, FOXO1 data from 165 EOC tissues, 46 borderline tumors, 42 benign tumors, and 57 nonadjacent normal epithelial tissues, as well as PAX3 data from 167 EOC tissues, 42 borderline tumors, 31 benign tumors, and 70 nonadjacent normal epithelial tissues could be interpreted." (PMID 31823759, 2019).
psychiatric disorder (1 paper, 2020). A disorder characterized by behavioral and/or psychological abnormalities, often accompanied by physical symptoms. "Some evidences showed that FoxO1 could express in hippocampus and corpus striatum, FoxO1 may contribute to the pathological process of MDD or other psychiatric disorders." (PMID 32792993, 2020).
FOXO1 also shares sentences with these, for which no sentence is quoted: soft tissue sarcoma (16 papers); embryonal rhabdomyosarcoma (12); hemangioma (6); liposarcoma (4); soft tissue tumor (4); acute pancreatitis (3); childhood cancer (3); clear cell sarcoma (3); gastrointestinal stromal tumor (3); Huntington disease (3); nephritis (3); small cell lung carcinoma (3); acute leukemia (2); adenomyosis (2); age (2); cervical adenocarcinoma (2); chronic prostatitis (2); chronic thromboembolic pulmonary hypertension (2); cystic fibrosis (2); disc degeneration (2); endometrial adenocarcinoma (2); female reproductive system diseases (2); fibrosarcoma (2); hepatic (2); intervertebral disc degeneration (2); kidney failure (2); low grade glioma (2); medulloblastoma (2); mesenchymal tumors (2); myxoid liposarcoma (2).
A further 139 diseases each share a sentence with FOXO1 in 2 papers or fewer.